NAF1 (nuclear assembly factor 1 ribonucleoprotein)
Diseases named in the same sentence as NAF1 in open-access papers (continued):
Sharing a sentence is not in itself a finding about the gene and the disease.
esophageal cancer (1 paper, 2017). A primary or metastatic malignant neoplasm involving the esophagus. "Our results demonstrated that the genotype AG of rs2320615 in NAF1 was associated with a significantly reduced risk of esophageal cancer." (PMID 28454086, 2017). "Our data demonstrated that the rs2320615 in NAF1 was associated with significantly reduced risk of esophageal cancer." (PMID 28454086, 2017). "In conclusion, the current study has identified that rs2320615 in the NAF1 was associated with the risk of esophageal cancer in the Han Chinese population." (PMID 28454086, 2017). "Our results suggested that NAF1 polymorphisms are associated with the risk of esophageal cancer." (PMID 28454086, 2017). "Given the importance of telomere length and the NF-κB signaling pathway in the development and maintenance of esophageal cancer, we hypothesized genetic polymorphisms in NAF1 and TNIP1 may influence esophageal cancer susceptibility." (PMID 28454086, 2017). "However, it remains unclear whether these NAF1 polymorphisms affect telomere length by affecting specific protein synthesis and function, and ultimately the susceptibility to esophageal cancer." (PMID 28454086, 2017). "This case-control study was designed to investigate whether genetic variants of NAF1 and TNIP1 were associated with the risk of esophageal cancer in the Han Chinese population." (PMID 28454086, 2017). "We investigated whether single nucleotide polymorphisms (SNPs) in the nuclear assembly factor 1 (NAF1) and TNFAIP3-interacting protein 1 (TNIP1) gene were associated with susceptibility to esophageal cancer in a Chinese Han population." (PMID 28454086, 2017).
insulinoma (1 paper, 2021). "We selected the murine insulinoma INS-1E cells for assessing the consequences of NAF-1 deficiency on pancreatic β-cells of WFS-T2 primarily on the basis that these cells respond to glucose stimuli by secreting insulin." (PMID 34439408, 2021). "We then assessed to what extent the elevated mitochondrial labile iron (mLI) and ROS (mROS) observed in NAF-1(−) insulinoma cells contributed to impaired stimulated insulin secretion, and whether alleviating mLI and mROS accumulation will improve glucose-stimulated insulin secretion." (PMID 34439408, 2021). "The rise in mLI, mROS, and cytosolic Ca2+ levels, upon NAF-1 depletion, and the finding that this rise could be suppressed by treatment with NAC and/or DFP, could suggest that NAF-1 deficiency in insulinoma cells triggers ferroptosis." (PMID 34439408, 2021).
lung adenocarcinoma (1 paper, 2015). A carcinoma that arises from the lung and is characterized by the presence of malignant glandular epithelial cells. "Even after dropping the three SNPs showing nominally significant (P < 0.05) association with lung adenocarcinoma (in TERT, OBFC1 and NAF1) the association is still significant (OR = 1.54, P = 0.018)." (PMID 26138067, 2015).
nonalcoholic steatohepatitis (1 paper, 2024). "Here, NAF-1 is a recently identified mitochondrial drug target for nonalcoholic steatohepatitis (NASH)." (PMID 38252831, 2024).
rheumatoid arthritis (1 paper, 2012). A chronic, systemic autoimmune disorder characterized by inflammation in the synovial membranes and articular surfaces. "For example, Naf1 is highly involved in NF-κB pathway activation in rheumatoid arthritis, while Stat5b activation occurs during proliferation/oxidation-associated production of advanced glycation end products." (PMID 22558133, 2012).
viral infection (1 paper, 2025). "Next, we evaluated Naf1’s modulation of viral infection in the presence of Nef." (PMID 40272155, 2025).
cancer (19 papers, 2015 to 2022). A tumor composed of atypical neoplastic, often pleomorphic cells that invade other tissues. "Lower NAF1 expression in the tumors drives the cancer towards a more aggressive phenotype because the risk SNP rs17042479(G) is associated with metastasizing tumors (stage 4) as well as right-side location of the tumor." (PMID 36067202, 2022). "The association of NAF-1 function with altered iron and ROS metabolism gained further support from studies conducted in cancer cells." (PMID 34439408, 2021). "A recent study demonstrated, for example, that if the CDGSH domain of NAF-1 is mutated from a 3Cis-1His coordinating structure to a 4Cis coordinating one (a single aa mutation that stabilized the cluster 25-fold over), NAF-1 loses its key function in promoting cellular proliferation in cancer cells." (PMID 29556009, 2018). "Gain and loss of function analysis of mNT and NAF-1 in cancer cells revealed that overexpression of mNT or NAF-1 protein promotes cancer cell proliferation, while suppression of either mNT or NAF-1 protein expression via shRNA decreases cancer cell proliferation and tumor growth." (PMID 28426722, 2017). "The alterations in Fe ion and ROS metabolism caused by NAF-1 suppression could have a dramatic effect on many different pathways in cancer cells, causing the activation of apoptosis and the suppression of tumor growth." (PMID 26621032, 2016). "NAF-1, mNT and Anamorsin have each been implicated in cancer." (PMID 26448442, 2015). "Because the constitutive suppression of NEET protein function has a deleterious effect on plant or animal cells, we recently used the Dexamethasone (DEX)-inducible system to drive the expression of NAF-1 or its H114C dominant-negative mutant in cancer cells." (PMID 36009251, 2022). "In a previous study we demonstrated that the inducible expression of the NAF-1 H114C mutant (with a high 2Fe-2S cluster stability) in cancer cells results in the enhanced expression of TXNIP that binds TRXs and induces oxidative stress and ferroptosis." (PMID 36009251, 2022). "To investigate the effect of SNP rs17042479 on cancer characteristics and the NAF1 expression, along with the NAF1 expression impact on cancer characteristics we analyzed a clinical dataset from patients diagnosed with CRC." (PMID 36067202, 2022). "The suppression of NAF-1 in cancer cells, which disrupts the Fe balance, can reduce cancer cell survival by affecting mitochondrial integrity and causing cancer cell death." (PMID 33669111, 2021). "Cell models showed that NAF-1 plays an important role in the regulation of cellular iron, calcium and ROS homeostasis, lipid, and glucose homeostasis, as well as cancer cell proliferation and tumor growth." (PMID 34946818, 2021). "Accumulating data demonstrates that NAF-1 functions as a prognostic signature and its up-regulation occurs in cancer cells." (PMID 32163546, 2020). "As a protein located on OMM, NAF-1 inhibition by resveratrol sensitizes cancer cells into apoptosis." (PMID 32163546, 2020). "Further support for the involvement of NAF-1 in autophagy/apoptosis regulation comes from studies in cancer cell lines, xenograft tumors and the null NAF-1 mouse model, in which NAF-1 dysfunction led to the activation of apoptosis." (PMID 29666474, 2019). "CISD2 encodes NAF-1, also a membrane-anchored homodimer that is localized to the ER, OMM and the membranes that connect them, and is involved in cancer, neurodegeneration, skeletal muscle maintenance, aging and the regulation of autophagy and apoptosis." (PMID 29556009, 2018). "Despite these possible differences, suppressing mNT or NAF-1 expression in cancer cells resulted in a similar phenotype of over-accumulation of iron and ROS in mitochondria and activation of autophagy." (PMID 28426722, 2017). "Further studies are needed to dissect the different cellular pathways mediated by mNT and NAF-1 in cancer cells." (PMID 28426722, 2017).
cancer (continued). "Overexpression of mNT also protects cells from oxidative stress and ferroptosis, whereas overexpression of NAF-1 protects cancer cells from oxidative stress and apoptosis." (PMID 28426722, 2017). "The NEET proteins mitoNEET (mNT) and nutrient-deprivation autophagy factor-1 (NAF-1) are required for cancer cell proliferation and resistance to oxidative stress." (PMID 28426722, 2017). "Suppression of mNT or NAF-1 protein expression also results in the over-accumulation of iron and ROS in the mitochondria of cancer cells and the activation of autophagy and apoptosis." (PMID 28426722, 2017). "Alterations in NAF-1 expression therefore affect major gene networks and metabolic pathways involved in the survival and proliferation of cancer cells." (PMID 26621032, 2016). "Our studies suggest that NAF-1 is a major player in the metabolic pathways of cancer cells through its effects on cellular distribution of Fe ions, mitochondrial ROS formation, stabilization of HIF1α and induction of apoptosis." (PMID 26621032, 2016). "The higher dependency on glycolysis observed in NAF-1(−) cells is also interesting because it points to a key role for NAF-1 in regulating energy metabolism in cancer cells, potentially linking the distribution of Fe ions in these cells with energy metabolism." (PMID 26621032, 2016). "To initiate a more detailed study into the response of cancer cells to NAF-1 suppression, we used western blotting to study the levels of selected proteins involved in these pathways in MCF-7 and MDA-MB-231 cells." (PMID 26621032, 2016). "In this study, we identified Anamorsin as the first human 2Fe-2S cluster acceptor protein for both the OMM cancer related mNT and NAF-1 proteins." (PMID 26448442, 2015). "This analysis revealed that in addition to enhanced mitochondrial iron and ROS levels, the suppression of NAF-1 function in cancer cells resulted in the enhanced expression of thioredoxin interacting protein (TXNIP), which binds thioredoxin (TRX) and induces oxidative stress." (PMID 36009251, 2022). "Furthermore, we investigated a clinical dataset analyzing details about CRC patients’ cancer characteristics and their NAF1 expression in tumor and healthy tissue, as well as their genotype at the risk locus at 4q32.2, SNP rs17042479." (PMID 36067202, 2022). "Indeed, several studies showed how different human cancer cells contains significantly increased levels of mitoNEET and NAF-1, which play a critical role in promoting tumor growth and metastasis." (PMID 36500311, 2022). "In order to investigate the possible role of the risk locus at 4q32.2 in CRC, we analyzed the relationship between the SNP rs17042479 (A/G), NAF1 expression and cancer characteristics in well-characterized biobank containing data and samples from 237 CRC patients." (PMID 36067202, 2022). "The association between SNP rs17042479(G) and the increased risk of developing CRC could be explained by a changed expression of NAF1 mediated through the gene regulatory effect of SNP rs17042479(G) affecting cancer characteristics." (PMID 36067202, 2022). "Thus, when overexpressed in cancer cells, a NAF-1 mutant with a 25-fold more stable 2Fe-2S cluster (H114C) was unable to promote cellular proliferation and protect cells from oxidative stress and apoptosis." (PMID 28426722, 2017). "To determine whether mNT and NAF-1 function in the same, or different pathways to mediate these functions in cancer cells we generated double shRNA cell lines with suppressed expression of both mNT and NAF-1." (PMID 28426722, 2017). "To test this possibility we used a combination of cell biology, omics and protein-protein interaction techniques to determine whether NAF-1 and mNT interact and function in the same pathway in cancer cells." (PMID 28426722, 2017).
cancer (continued). "Moreover, the function of NAF-1 in protecting cancer cells from oxidative stress and promoting cellular proliferation is dependent on the degree of lability of the NAF-1 2Fe-2S cluster during oxidative stress." (PMID 28426722, 2017). "This high degree of overlap between the transcripts altered in mNT(-) and NAF-1(-) suggests that the majority of responses induced by mNT suppression are also induced by NAF-1 suppression and that these transcripts may hint to the similar function these two proteins are mediating in cancer cells." (PMID 28426722, 2017). "NAF-1 could therefore be required for proper Fe-S biogenesis or mobilization in cancer cells." (PMID 26621032, 2016). "Cancer cells produce CISD2 (nutrient deprivation autophagy factor-1; NAF-1), a metal-sulfur [2Fe-2S] homodimer protein that acts as a prognostic marker in a variety of cancers." (PMID 36338346, 2022). "Interestingly, the results showed that resveratrol could significantly promote the cancer cell death via sequentially inducing Nrf2 upregulation and NAF-1 downregulation, while the siRNA designed for Nrf2 markedly blocked the proapoptosis effect induced by resveratrol." (PMID 29765509, 2018).
tumor (12 papers, 2016 to 2022). "The patients with the risk SNP rs17042479(G) were associated with lower expression of NAF1 compared to patients with the reference SNP rs17042479(A) in tumor tissue." (PMID 36067202, 2022). "This suggests that low NAF1 expression in tumor tissue is associated with a poor prognosis for CRC patients." (PMID 36067202, 2022). "Patients harboring the risk allele of SNP rs17042479(G) had a significantly lower relative NAF1 expression in tumor tissue compared to patients with the reference allele of SNP rs17042479(A)." (PMID 36067202, 2022). "In addition, we analyzed if there was an association between the presence of risk SNP rs17042479(G) and the NAF1 expression in healthy and tumor tissue." (PMID 36067202, 2022). "Conversely, a correlation was found between the NAF1 expression and the presence of the SNP rs17042479(G) in tumor tissue." (PMID 36067202, 2022). "The results in the study imply that reduced NAF1 expression in the tumor contribute to a more aggressive phenotype." (PMID 36067202, 2022). "In this regard, it has been shown that the inhibition of NAF-1 in PC cells causes an inhibition of PC stem cell characteristics and their ability to invade, demonstrating the important role of NAF-1 in tumor progression." (PMID 33669111, 2021). "In vivo and in vitro experiments also confirmed that NAF-1 can promote the proliferation and the tumorigenicity of tumor cells." (PMID 32766132, 2020). "Studies have found that NAF-1 is mainly involved in the regulation of oxidative stress and autophagy and is closely related to tumor growth." (PMID 32766132, 2020). "The results showed that xenograft tumors induced by U87 cells stably knocking down NAF1 grew slowly and exhibited a dramatic reduction of tumor volume and weight relative to control tumors." (PMID 30936423, 2019). "As reported in the literature, the suppression of NAF-1 results in the activation of apoptosis, prevention of tumors formation, and suppression of tumor growth." (PMID 29765509, 2018). "The number of tumor cells containing elevated levels of γH2AX, a marker for the activity of the DNA damage response pathway, was also high in tumors derived from NAF-1(−) cells compared to tumors derived from control cells." (PMID 26621032, 2016). "We investigated if the NAF1 expression differed between tumor and healthy tissue." (PMID 36067202, 2022). "In general, we found that NAF1 expression was lower in tumor tissue compared to healthy tissue." (PMID 36067202, 2022). "The NAF1 expression in tumor tissue was lower than the NAF1 expression in healthy tissue." (PMID 36067202, 2022). "Additionally, patients with SNP rs17042479(G) showed lower NAF1 expression in comparison to patients with SNP rs17042479(A) in tumor tissue and the NAF1 expression in tumor tissue was lower compared to healthy tissue." (PMID 36067202, 2022). "Interestingly, we found that the proportions of NMF and NAF1 were more prevalent in normal tissues than tumor tissues, while CAF2/3/4, VSMC, and pericytes were predominant in tumor tissues compared with normal tissues." (PMID 34489433, 2021). "Taken together, resveratrol could be an effective anti-tumor drug, and NAF-1 may be a rational therapeutic target." (PMID 32766132, 2020). "The activation of apoptosis in cells with suppressed NAF-1 expression could account for the decrease in tumor size that is observed in xenograft tumors produced from NAF-1(−) cells." (PMID 26621032, 2016). "Therefore, NAF-1 is likely to be an important part of the metabolic regulation of tumor stem cells." (PMID 32766132, 2020). "Therefore, it is hypothesized that NAF-1 plays an important role in tumor cells, actively participates in clinical therapy, and exerts a beneficial effect on the prognosis of patients." (PMID 29765509, 2018). "The NAF1 and Beta-2 Microglobulin (B2M) expression data from CRC patients were determined from tumor and healthy intestinal tissue samples, and whether the patients were genotyped for the SNP rs17042479." (PMID 36067202, 2022).
tumor (continued). "Among the tested cell lines, NAF-1 was also significantly expressed in non-activated Q-PSC, suggesting that NAF-1 also plays an important role in tumor-related PSC, which remains to be further explored and studied." (PMID 32766132, 2020).
infection (1 paper, 2025). The state of being infected such as from the introduction of a foreign agent such as serum, vaccine, antigenic substance or organism. "Naf1 transfection inhibited the infection of HIV-1 NL4-3 (∆Nef), as detected by the gag mRNA production, Naf1’s inhibition was abolished in the infection of HIV-1 NL4-3 containing Nef." (PMID 40272155, 2025).
neurodegenerative disease (1 paper, 2017). A disorder of the central nervous system characterized by gradual and progressive loss of neural tissue and neurologic function. "This could be reflected by the important role NAF-1 currently plays in neurodegenerative diseases." (PMID 28205535, 2017).
NAF1 also shares sentences with these, for which no sentence is quoted: pulmonary fibrosis (3 papers); cardiovascular disease (1); ependymoma (1); gastric cancer (1); glioblastoma (1); heart disease (1); hemochromatosis (1); interstitial lung disease (1); iron overload (1); laryngeal carcinoma (1); liver cancer (1); lung carcinoma (1); lymph node metastasis (1); prostate carcinoma (1); sideroblastic anemia (1).